GPX4 (glutathione peroxidase 4)
Diseases named in the same sentence as GPX4 in open-access papers (continued):
Sharing a sentence is not in itself a finding about the gene and the disease.
cancer (continued). "The fine mechanisms that regulate Gpx4 show great potential for treating ferroptosis-related cancer." (PMID 38684666, 2024). "Initially identified as a positive regulator of mitochondrial apoptosis, AIFM2 translocates from mitochondria to the plasma membrane in GPX4-low-expressing cancer cells when stimulated with ferroptosis inducers (e.g., RSL3 and ML162)." (PMID 38844964, 2024). "The cysteine/GSH/GPX4 mechanism is widely employed in ferroptosis-related nanoparticle cancer therapy research." (PMID 39614322, 2024). "Among ferroptosis negative regulation (FNR) genes, GPX4 is a core repressor of ferroptosis in cancer cells." (PMID 38842940, 2024). "GPX4, as one of the most significant antioxidant enzymes, has gained considerable attention over the past decade due to its pivotal regulatory role in cancer, cardiovascular disease, and neuroscience research." (PMID 38650929, 2024). "In the case of GPx4, it has been shown that its inactivation results in an effective eradication of cancer cells by inducing cell death through ferroptosis." (PMID 38891864, 2024). "This process escalates the expression and activity of GPX4, making cancer cells more resilient against ferroptosis and thus fostering cancer cell metastasis." (PMID 38217037, 2024). "High levels of glutathione (GSH) are observed in the majority of tumors, contributing to cancer progression and treatment resistance in part by preventing glutathione peroxidase 4–dependent (GPX4-dependent) ferroptosis." (PMID 38441967, 2024). "Ferroptosis has emerged as an effective approach to cancer therapy, and it involves four main pathways: iron metabolism, GPX4 regulation, lipid metabolism, and a novel sex hormone-related pathway." (PMID 38493165, 2024). "Inhibiting xCT and GPX4 has been identified as a mechanism to induce cancer cell death in response to conventional chemotherapy or radiotherapy." (PMID 38469234, 2024). "GPx4’s role in the regulation of ferroptosis and oxidative damage makes it a compelling target for cancer therapy, especially in PDAC." (PMID 39594547, 2024). "GEPIA online databases were used to analyze GPX4's expression level in different types of normal tissues and human cancer." (PMID 38333875, 2024). "In comparison, artemisinin enhances the ferroptosis of cancer cells by downregulating the ferroptosis-inhibiting GPX4 gene." (PMID 38892270, 2024). "Recent reviews emphasize the role of GPX4 as a critical modulator of ferroptosis and its potential in overcoming drug resistance in cancer treatments." (PMID 39944353, 2024). "GPX4, which is essential for cancer cell survival and is expressed in the majority of cancer cell lines, is possibly the most obvious target." (PMID 39055871, 2024). "RSL3 binds directly to GPX4, inhibiting the action of GPX4, thus blocking the pathway that protects cancer cells from ferroptosis." (PMID 38672271, 2024). "In cancers predicated on GPX4 dependency, Cys availability emerges as a pivotal determinant of neoplastic resistance to ferroptosis." (PMID 38217037, 2024). "Glutathione peroxidase 4 (GPX4) is a key regulator of ferroptosis, and agents that inhibit the activity of GPX4 have been developed for cancer therapy." (PMID 38675144, 2024). "Overall, the multifaceted role of GPX4 makes it an intriguing focal point for therapeutic interventions and demonstrates its potential to shape the future of cancer therapy." (PMID 39090114, 2024). "This will be crucial as GPX4 seems to be a key component in ferroptosis but its function seems ambivalent depending on the cancer line it is studied in." (PMID 39309484, 2024).
cancer (continued). "Persister cancer cells were reported to be vulnerable to inhibition of GPx4, leading to enhanced lipid peroxidation and ferroptosis, thus suggesting the potential of targeting lipid peroxidation pathways to overcome drug resistance in cancer cells." (PMID 39169426, 2024). "To investigate the anti-cancer effect of NRF2 inhibitors combined with GPX4 inhibitors, we chose three NRF2 inhibitors (trigonelline (TRI), Clobetasol propionate (CP), and ML385) and two GPX4 inhibitors (RSL3 and ML210)." (PMID 38396022, 2024). "Refractory cancers can potentially benefit from the inhibition of GPX4, which is considered a promising therapeutic target and prognostic marker in various cancer types." (PMID 38816377, 2024). "GPX4, as the principal orchestrator of ferroptosis, has garnered significant attention across cancer, cardiovascular, and neuroscience domains over the past decade." (PMID 39036600, 2024). "This pathway operates independently of the GPX4/glutathione axis, providing an alternative mechanism for cancer cells to evade ferroptotic cell death." (PMID 39759144, 2024). "A cold-vulnerable human cancer cell line becomes resistant to severe cold (4°C) exposure and rewarming by heterologous expression of Syrian hamster GPx4, which suppresses lipid peroxidation." (PMID 38725569, 2024). "GPX4 protects cancer cells against oxidative damage, inhibits ferroptosis and can have an oncogenic effect in multiple cancers." (PMID 36626251, 2023). "Based on this, several ferroptosis-inducing agents (FINs) that target GPX4 or cystine-glutamate antiporters have been developed and are regarded as potential drugs for cancer treatment." (PMID 37714840, 2023). "Heat shock protein family A member 5 (HSPA5) increased by activation of ATF4 inhibits lipid peroxidation in ferroptosis by protecting against GPX4 degradation in cancer cells." (PMID 37458878, 2023). "Cancer cells with a mesenchymal state that usually become resistance to conventional therapies (i.e., apoptosis inducers) are strongly dependent on GPX4, which is related to upregulated expression of zinc finger E-box binding homeobox 1 (ZEB1)." (PMID 37795022, 2023). "Dihydroisotanshinone I induced ferroptosis in two types of cancer cells by increasing intracellular lipid peroxidation and inhibiting the expression of the GPX4 protein." (PMID 37833746, 2023). "Our results demonstrated that N6-methyladenosine (m6A) and 5-methylcytosine (m5C) modification of GPX4 activates STING by maintaining redox homeostasis during cancer immunotherapy." (PMID 38065948, 2023). "GPX4 is highly expressed in cancer cells where it can arrest ferroptosis, enhancing the anticancer effects of cisplatin." (PMID 37240889, 2023). "The inactivation of DHODH sensitizes GPX4-high cancer cells to ferroptosis inducers and enhances ferroptosis in GPX4-low cancer cells." (PMID 37762411, 2023). "Remarkably, pharmacological targeting of FSP1 in combination with GPX4 inhibitors shows a potent synergy in inducing ferroptosis in various cancer types." (PMID 37894808, 2023). "This overexpression of GPX4 in AML patients highlighted a potentially efficacious drug target in this cancer, and both studies found that inhibition of GPX4 with ML210 or RSL3 induced the death of AML cells in vitro." (PMID 37108836, 2023). "Inactivation of SLC7A11 or GPx4 with FINs can sensitize radiation-resistant cancer cells and xenografts to IR." (PMID 37007068, 2023). "β-cateninΔ(ex3)/+ MEFs were more resistant to erastin-induced ferroptosis, which was consistent with glutathione peroxidase 4-mediated ferroptosis resistance in β-catenin-activated cancers." (PMID 36703130, 2023). "Inhibiting the expression of GPX4 induces ferroptosis in cancer cells and boosts the anticancer effect of cisplatin. cAMP response element-binding protein (CREB) is upregulated in LUAD." (PMID 38072908, 2023).
cancer (continued). "It was found that the activated CD8+ T cells and CD4+ T cells were more sensitive to GPX4 inhibitors than antigen-expressing cancer cells in an in vitro co-culture system." (PMID 36926345, 2023). "Accordingly, upregulation of GPX4 has been reported to function as a major suppressor of ferroptosis in cancer cells." (PMID 36978786, 2023). "The antitumor experimentsand the analysis of the levels of GPX4 and intracellular iron confirmedthe benefits and efficiency to amplify ferroptotic cancer cell deathusing the combined AIEgen-based system for cancer therapy." (PMID 37486125, 2023). "The FSP1-CoQ pathway has been identified as a second ferroptosis suppressive mechanism, which acts in parallel to glutathione peroxidase GPX4 and which renders some cancer cell lines refractory to ferroptosis upon GPX4 inhibition." (PMID 36658222, 2023). "Some inflammatory cytokines (such as TNF, PGE2, IL-1β, IL-6, and IL-1) directly influence the level and activity of GPX4 in cancer cells." (PMID 38130953, 2023). "A study has shown that dihydroorotate dehydrogenase attenuates ferroptosis induced by GPX4 inhibition in cancer cells." (PMID 36645171, 2023). "FZKA was also found to decrease the level of GPX4 protein and mRNA and induce ferroptosis in cancer cells by increasing lipid peroxidation and intracellular levels of ferrous ions, which was also found in vivo." (PMID 37833746, 2023). "Consistent with the results of the correlation analysis, a marked infiltration of immune cells associated with cancer immunotherapy, including CD8 + T cells, was observed in the GPX4 high-subgroup." (PMID 38065948, 2023). "Meanwhile, other studies have shown that GPX4, a key enzyme for intracellular glutathione synthesis, is significantly over expressed in 13 cancers." (PMID 37207153, 2023). "In a variety of cancer cell lines, including gastric, pancreatic, and colorectal cancers, piperlongumine inhibits GPX4 activity mainly by reducing GSH, leading to ROS accumulation." (PMID 37408372, 2023). "It is thus imperative to find an effective intervention approach for targeting GPX4 to improve the anti-cancer effects via ferroptosis induction." (PMID 37554285, 2023). "In this scenario, these results show that in addition to the depletion of GPX4, delocalization/inaccessibility of this protein to lipid droplets must occur to favor its peroxidation and trigger ferroptosis in cancer cells resistant to IKE." (PMID 37752118, 2023). "GPX4 can affect the production of inflammatory factors, function of immune cells, metabolism of substances, and development of cancer." (PMID 38130953, 2023). "For example, the small molecule RSL3 binds to and inhibits GPx4 in cells and induces ferroptosis in many sensitive cancer cell lines." (PMID 36595221, 2023). "EMT properties and cancer metastasis can be suppressed by downregulating YAP/TAZ, and LYRIC, the positive regulator of EMT, can prevent cancer metastasis by inhibiting the expression of GPX4 and SLC3A2 to promote ferroptosis." (PMID 38130953, 2023). "The further study of the role of GPX4 in the development and therapy of cancer will contribute to a better understanding and application of this strategy." (PMID 38023171, 2023). "The cytotoxic activity of HO‐1‐inducing small molecules on cancer cells seems to rely on the concomitant drop in GPX4 levels, which is shared by the compounds here presented." (PMID 36658724, 2023). "Nonetheless, many covalent GPX4 inhibitors are toxic to both cancer and normal cells, potentially because they are confronted by poor selectivity." (PMID 36658724, 2023). "The results of this study provide a new direction for the development of cancer therapy targeting the SLC7A11/GPX4 pathway." (PMID 37266741, 2023). "Similar to GPX4-dependent mesenchymal resistant cancer cells, persistently drug-resistant cancer cells are also highly sensitive to ferroptosis." (PMID 37051544, 2023).
cancer (continued). "In cancer cells, glutathione peroxidase 4 (GPX4) converts lipid hydroperoxides to lipid alcohols, thereby reducing lipid peroxidation, membrane oxidative damage, and ferroptosis." (PMID 38036507, 2023). "FINO2 is an endoperoxide-containing 1,2-dioxolane that can oxidize Fe(II) and repress GPX4 enzymatic catalytic activity indirectly, which leads to extensive lipid peroxidation, aggravating the ferroptosis process of cancer cells." (PMID 37065473, 2023). "Numerous inflammatory cytokines, such as TNF, PGE2, IL-1, IL-6, and IL-1, have been reported to have a direct effect on the levels and activity of GPX4 in cancer cells." (PMID 37598126, 2023). "Many bioactive compounds isolated from herbs or small molecules have been identified as ubiquitination inducers targeting GPX4 to activate ferroptosis in cancer cells." (PMID 36951540, 2023). "The formation of tumors, activation of systemic Xc-transporters, increased GSH metabolism and GPX4 activity, inhibition of lipid peroxidation, and iron metabolism are all effects of ferroptosis inhibition in cancer." (PMID 37598126, 2023). "For example, a compound called NPD4928, identified from a chemical library, has shown the ability to enhance the cytotoxicity of GPX4 inhibitors in various cancer cells by specifically targeting FSP1." (PMID 37371948, 2023). "GPX4 drives the most powerful defense against ferroptosis and some drug-resistant/tolerant cancer cells are considerably vulnerable to GPX4-mediated ferroptosis." (PMID 37580393, 2023). "A high glutathione peroxidase 4 expression level was found in 7 (16.67%) cancer tissues and 0 (0.00%) paracancerous tissues (P = .012)." (PMID 37768308, 2023). "In the high-GPX4 expression subgroup, the activities of most steps within the cancer immunity cycle were significantly higher than those of the low-GPX4 subgroup." (PMID 38065948, 2023). "The cysteine, glutamate, and glycine consist of the tripeptide GSH which plays important roles in the GPX4-mediated ferroptosis in cancer cells." (PMID 36926345, 2023). "Further investigation revealed that cancer cells supplemented with G3P attenuated ferroptosis induced by GPX4 inhibitors in a GPD2-dependent manner." (PMID 38155662, 2023). "Many classical ferroptosis inducers, such as erastin and RAS-selective lethal 3, can target the xCT/GPX4 axis, and these inducers can trigger ferroptosis in cancer cells, suggesting they hold promise in the treatment of cancer." (PMID 37770442, 2023). "GPx4 is the core regulator of ferroptosis, and direct targeting of GPx4 to induce ferroptosis in cancer cells is a potential strategy for developing anticancer agents." (PMID 36923926, 2023). "Cancer drug-tolerant persister cells are vulnerable to GPX4 inhibition because of the upregulated GPX4, which has been identified as a likely target molecule." (PMID 36713828, 2023). "Drug-resistant and highly mesenchymal cancer cells depend on GPX4 activity to repress ferroptosis and survive." (PMID 37325669, 2023). "The top 10 keywords in terms of occurrence were “ferroptosis”, “prognosis”, “apoptosis”, “cancer”, “iron”, “lipid peroxidation”, “autophagy”, “cell death”, “Gpx4”, and “immunotherapy” in the field of “ferroptosis in cancer”." (PMID 37061535, 2023). "Therapy‐resistant cancer cells with more property of epithelial–mesenchymal transition are more sensitive to GPX4 inhibition or statin treatment induced ferroptosis." (PMID 38124786, 2023). "Previous studies have shown that GPX4 plays a crucial role in ferroptosis and chemoresistance in human cancers." (PMID 37198609, 2023). "The result suggested that the low dose of GPX4 inhibitors will benefit the growth of cancer cells by selectively inhibiting the killing function of CD8+ T cells." (PMID 36926345, 2023). "Triggering ferroptosis in cancer cells has shown promising effects in cancer therapy by targeting key regulators such as GPX4 and SLC7A11, the key regulators of this form of cell death." (PMID 37558749, 2023).
cancer (continued). "A deeper understanding of the mechanism and application of GPX4-mediated ferroptosis in cancer therapy will provide new strategies for the research and development of antitumor drugs." (PMID 36675129, 2023). "Inactivation of SLC7A11 or GPX4 with ferroptosis inducers (FINs) can make radioresistant cancer cells and xenograft tumors sensitive to ionizing radiation, indicating the potential significance of radiotherapy combined with FINs in cancer treatment." (PMID 37714846, 2023). "No drug specifically targets mGPX4, but the feasibility of developing general GPX4 inhibitors for cancer therapy has been verified with many cancer models, including melanoma, renal cell carcinoma, small cell lung cancer, breast cancer, and other models." (PMID 37580393, 2023). "A drop in GPX4 levels is expected to be more challenging for cancer cells than for normal cells because of their high metabolic turnover that is associated with oxidative stress." (PMID 36658724, 2023). "Although the mechanisms underlying ferroptosis are not fully clarified, RSL3 has been used as a potent ferroptosis triggering agent in many types of cancer, inhibiting GPX4 activity." (PMID 37924062, 2023). "This is normally kept in check by abundant expression of GPX4, an antioxidant enzyme, in cancer cells." (PMID 37183818, 2023). "Nevertheless, as research progresses, it has become evident that the responsiveness of various cancer cell lines to GPX4 inhibitors exhibits significant variability." (PMID 37868994, 2023). "Modulating the pathways and factors involved in ferroptosis, such as targeting GPX4, can induce ferroptosis in cancer cells and offer potential therapeutic opportunities." (PMID 38155662, 2023). "It is a type of cancer liable to ferroptosis induction, e.g., enzalutamide therapy results in GPX4 inhibition and consequent ferroptosis sensitization." (PMID 37480146, 2023). "We also confirmed that PACMA31 has high in vitro potency to kill cancer cells and directly binds to GPX4, as evidenced by a band shift." (PMID 37714840, 2023). "The results showed obviously higher GPX4 expression in cancer tissues than in paracancerous tissues (N=16)." (PMID 36626251, 2023). "The induction of ferroptosis is an attractive strategy for cancer therapy because a single inhibitor of GPX4 or SLC7A11 can markedly induce ferroptosis in cells." (PMID 37714840, 2023). "The most common ferroptotic pathway employed in cancer therapy is glutathione peroxidase 4 (GPX4) and glutathione (GSH) signaling." (PMID 37550282, 2023). "Interactions between GPX4 and several biological processes and the cancer immune cycle were evaluated in the TCGA-COAD cohort." (PMID 38065948, 2023). "Then, we detected GPX4 expression by qRT-PCR and western blot assays in cancer tissues and corresponding paracancerous tissues." (PMID 36626251, 2023). "This approach of combining NPD4928 with GPX4 inhibitors holds promise as a potential therapeutic strategy for inducing ferroptosis in cancer cells." (PMID 37371948, 2023). "In summary, our study provides a first direct link between mitochondrial calcium level and sustained GPX4 enzymatic activity to regulate ferroptosis, which consequently protects cancer cells from ferroptosis." (PMID 37502961, 2023). "Cytoglobin (CYGB) and glutathione peroxidase 4 (GPX4) are two members of this protein family whose modification by CAP-generated RONS can be effective in cancer therapy, and they have been studied at the atomic scale using MD simulations." (PMID 37759771, 2023). "Next, we investigated the relevance of GPx4 through integrative analysis of complex cancer genomics and clinical profiles using cBioPortal." (PMID 36768241, 2023).